SNORC (secondary ossification center associated regulator of chondrocyte maturation)
Description:
Plays a role in the regulation of chondrocyte maturation and postnatal endochondral ossification. May inhibit cell growth stimulation induced by FGF2.
Synonyms: C2orf82; UNQ830; ASCL830
Tractability: Antibody: UniProt places it where antibodies can reach, with medium confidence; UniProt predicts a signal peptide or a membrane-spanning region; its Gene Ontology location is reachable by antibodies, with medium confidence.
Gene: Protein-coding gene on chromosome 2 (232,857,270 to 232,878,708, forward strand). Ensembl gene ENSG00000182600.
Subcellular location: Membrane; Cytoplasm; Secreted, extracellular space, extracellular matrix
Subcellular location (Human Protein Atlas): Nucleoli; Nucleoplasm
Gene Ontology:
Molecular function: protein binding
Biological process: cartilage development
Cellular component: cell periphery; cytoplasm; membrane
Genetic constraint (gnomAD): Loss-of-function variants: 11 observed, 5.08 expected, observed/expected ratio (o/e) 2.17. That is too few expected variants to judge how well the gene tolerates losing a copy. Missense variants: 197 observed, 118.07 expected, observed/expected ratio (o/e) 1.67, 90% interval 1.49 to 1.87. Synonymous variants: 108 observed, 61.31 expected, observed/expected ratio (o/e) 1.76, 90% interval 1.5 to 1.96.
Homologues: Orthologues: chimpanzee SNORC (100% identical), macaque SNORC (99% identical), dog SNORC (88% identical), guinea pig SNORC (88% identical), pig SNORC (87% identical), mouse Snorc (81% identical), rat Snorc (65% identical).
Diseases named in the same sentence as SNORC in open-access papers:
SNORC is named in the same sentence as 4 diseases in open-access papers, as found by Europe PMC text mining. Sharing a sentence is not in itself a finding about the gene and the disease.
SNORC shares sentences with these, for which no sentence is quoted: developmental delay (1 paper); major depressive disorder (1); osteoarthritis (1); psychiatric disorder (1).